ZFP36L1 (ZFP36 like 1 zinc finger CCCH-type)
Diseases named in the same sentence as ZFP36L1 in open-access papers (continued):
Sharing a sentence is not in itself a finding about the gene and the disease.
Obesity (4 papers, 2017 to 2026). Accumulation of substantial excess body fat. "While our studies focused on the role of ZFP36L1 in aging-related bone loss, the finding that ZFP36L1 was able to regulate adipogenesis raises a question as to whether this molecule may also play a potential role in obesity." (PMID 28206953, 2017). "Therefore, it will be of interest to examine if ZFP36L1 is involved in the mechanisms by which microRNAs and the circulating factors regulate adipogenesis and obesity." (PMID 28206953, 2017). "Mice lacking hepatic ZFP36L1 exhibit resistance to diet-induced obesity and hepatosteatosis." (PMID 40732992, 2025).
Acute Myeloid Leukaemia (3 papers, 2012 to 2021). "However, although ZFP36L1 has generally been considered a tumour suppressor gene, in acute myeloid leukaemia cells carrying the AML-ETO1 translocation, ZFP36L1 is overexpressed and is associated with increased proliferation and inhibition of differentiation." (PMID 35008519, 2021). "ZFP36L1 has also been found to be overexpressed in cell lines and primary cells expressing the AML1-ETO fusion protein that is found in 40% of Acute Myeloid Leukaemia of M2 sub-type." (PMID 23284928, 2012).
colorectal cancer (3 papers, 2018 to 2024). A primary or metastatic malignant neoplasm that affects the colon or rectum. "In many carcinomas (e.g., liver carcinoma, lung carcinoma and colorectal carcinoma), ZFP36L1 represses oncogenic protein expression and tumor progression, whereas in gastric carcinoma, ZFP36L1 promotes tumor progression." (PMID 37935976, 2024). "To confirm the effects of ZFP36L1 and ZFP36L2 on tumor cells, we used seven human colorectal cancer cell lines to screen expressions of ZFP36L1 and ZFP36L2 by using western blot analysis." (PMID 29426877, 2018). "With further detection of G1 phase-related molecule expressions, we found that forced expression of ZFP36L1 or ZFP36L2 markedly reduced cyclin D protein expression but did not change expressions of other molecules, including cyclin A, Cdk2, or Cdk4, in these three types of colorectal cancer cell." (PMID 29426877, 2018).
gastric cancer (3 papers, 2024 to 2025). A primary or metastatic malignant neoplasm involving the stomach. "Other risk genes include KDM1A, a histone demethylase implicated in oncogenic chromatin remodeling, and ZFP36L1, an RNA‐binding protein associated with inflammation and gastric cancer development." (PMID 40561176, 2025).
glioma (3 papers, 2021 to 2024). A benign or malignant brain and spinal cord tumor that arises from glial cells (astrocytes, oligodendrocytes, ependymal cells). "Through experiments in mouse and human glioma cells, Zfp36l1 was demonstrated to control the genesis and growth of gliomas." (PMID 33975628, 2021). "Furthermore, gliomas with higher expression of Zfp36l1 were more difficult to treat." (PMID 33975628, 2021).
multiple myeloma (3 papers, 2012 to 2021). "For example, in a subset of human B cell malignancies there are interstitial deletions of the ZFP36L1 locus at 14q24 and, recent whole genome sequencing of tumours from multiple myeloma patients has identified regulatory-region and coding-region mutations in the ZFP36L1 gene." (PMID 25014217, 2014). "Analysis of ZFP36L1 protein also revealed very low/absent levels of ZFP36L1 in myeloma cells compared to unstimulated and PMA-stimulated Ramos Burkitt lymphoma cells." (PMID 23284928, 2012). "All three cell lines of myeloma origin (representing plasma cells) expressed higher levels of BLIMP1 with either lower (JJN3, KMM1) or absent (MMIS) expression of ZFP36L1 mRNA." (PMID 23284928, 2012).
prostate carcinoma (3 papers, 2009 to 2026). A carcinoma that arises from epithelial cells of the prostate gland. "A prior network analysis nominated ZFP36L1 as a critical gene in metastatic prostate cancer, and our functional studies validated that prediction." (PMID 29340039, 2017). "We also observed concordant down-regulation of expression of TIMP3 and ZFP36L1 in both the enzalutamide-resistant MR49F cell line and metastatic CRPC prostate cancers." (PMID 29340039, 2017).
T-cell acute lymphoblastic leukemia (3 papers, 2018 to 2024). Acute lymphoblastic leukemia of T-cell origin. "Deletion of the genes Zfp36L1 and Zfp36L2, which encode RNA-binding proteins, was shown to cause T-cell acute lymphoblastic leukemia (T-ALL) in mice due to impaired Notch1 mRNA degradation." (PMID 30144809, 2018). "Previous work has shown that mice with double KO of Zfp36l1 and Zfp36l2 in T cells during thymopoiesis develop T cell acute lymphoblastic leukemia because of changes in Notch-1 signaling." (PMID 37903626, 2024). "Indeed, ZFP36L1 and ZFP36L2 suppressed NOTCH1 expression in T cell acute lymphoblastic leukemia by interacting with the 3′ UTR of NOTCH1." (PMID 37853162, 2023). "However, mice with single KO of Zfp36l1 or Zfp36l2 individually in T cells during thymic development do not develop T cell acute lymphoblastic leukemia, suggesting that Zfp36l1 and Zfp36l2 may have redundant functions in T cells." (PMID 37903626, 2024).
viral infection (3 papers, 2022 to 2025). "Recently, the zinc-finger protein ZFP36L1 was shown to enhance host anti-viral defense against influenza A virus, supporting a role of these proteins in response to viral infection." (PMID 35849620, 2022). "However, virus infection activates expression of ZFP36L1, an RNA-binding stress protein that limits the length and the intensity of the cytokine response." (PMID 37830871, 2023).
B cell lymphoma (2 papers, 2020 to 2023). "Additionally, we chose to look at BCL2 transcript stability as ZFP36L1 has been shown in B cell lymphoma to negatively regulate BCL2 transcript stability." (PMID 36376377, 2023).
Burkitt lymphoma (2 papers, 2012 to 2014). A rare form of malignant mature B-cell non-Hodgkin lymphoma. "For these experiments, cell lysates from Ramos Burkitt lymphoma B cells, which express high levels of ZFP36L1 in response to PMA stimulation, were used." (PMID 25014217, 2014). "In Eμ-Myc mice, a mouse model of human Burkitt lymphoma, and also in human Burkitt lymphoma versus non-Burkitt lymphomas, ZFP36 and ZFP36L1 were shown to be transcriptionally repressed." (PMID 25014217, 2014).
colon cancer (2 papers, 2021 to 2023). "qPCR showed that TTP and ZFP36L1 genes were expressed in similar levels but ZFP36L2 mRNA was barely detectable in the colon cancer cells." (PMID 37705049, 2023). "SYBR Green qPCR showed that TTP/ZFP36 and ZFP36L1 were expressed in similar levels but ZFP36L2 mRNA was barely detectable in the colon cancer cells." (PMID 33723275, 2021). "ZFP36, ZFP36L1 and ZFP36L2 mRNA levels were generally increased in the colon cancer cells by high concentration of LPS treatment." (PMID 37705049, 2023). "TTP family mRNA levels (ZFP36, ZFP36L1 and ZFP36L2 mRNAs) were generally decreased and TTP-targeted cytokine mRNA levels (TNF, COX2, PPARR and RAB24 mRNAs) were relatively high in the colon cancer cells." (PMID 33723275, 2021).
disc degeneration (2 papers, 2025 to 2026). "Though the common downregulation of Junb and Zfp36l1 is a substantial lead into how DQ may mediate disc degeneration, two genes/pathways are insufficient to fully capture the processes driving improved disc health outcomes." (PMID 40585254, 2025). "A comparison of SM/J data with DQ-mediated aging-dependent amelioration of disc degeneration in C57BL/6 N mice identified Junb and Zfp36l1 signaling as shared DQ targets in the mouse disc." (PMID 41974671, 2026). "A comparison with DQ-mediated aging-dependent amelioration of disc degeneration in C57BL/6N mice identified Junb and Zfp36l1 signaling as shared DQ targets in the mouse disc." (PMID 40585254, 2025). "Notably, our results show that DQ, but not Nav., reduces the severity of disc degeneration and senescence burden through targeting Jun and Zfp36l1 signaling pathways." (PMID 40585254, 2025).
glioblastoma (2 papers, 2020 to 2022). The most malignant astrocytic tumor (WHO grade IV). "In glioblastoma multiforme (GBM) cells, overexpression of miR-129-5p reduces ZFP36L1 expression and impairs cancer cell proliferation, migration, and invasion." (PMID 35884580, 2022).
influenza (2 papers, 2022 to 2025). An acute viral infection of the respiratory tract, occurring in isolated cases, in epidemics, or in pandemics; it is caused by serologically different strains of viruses (influenzaviruses) designated A, B, and C, has a 3-day incubation period, and usually lasts for 3 to 10 days. "Finally, while our data suggests that ZFP36 and ZFP36L1 are redundant in limiting T cell dependent resilience to influenza, different outcomes for the individual RBP might be found upon other immune challenges such as persistent infection." (PMID 35477960, 2022). "The top-ranked genes for influenza classification included IFI27, ZFP36L1, TNC, SERTAD2, and AMPD3, several of which are known interferon-stimulated or antiviral response genes." (PMID 41020849, 2025).
myelofibrosis (2 papers, 2020 to 2025). A partial or complete replacement of the bone marrow stroma by fibrous tissue. "While no clear overall association was found, some candidate genes exhibited concordant changes in DNAm and gene expression, such as hypermethylated and downregulated ZFP36L1, linked to myelofibrosis progression and INPP5D known to be downregulated by JAK2 V617F." (PMID 40319310, 2025). "Interestingly, ZFP36L1 was found to be downregulated due to enhancer hypermethylation within the second exon in myelofibrosis, which conversely led to an increased expression of its target mRNAs." (PMID 32545247, 2020).
osteoarthritis (2 papers, 2019 to 2022). A noninflammatory degenerative joint disease occurring chiefly in older persons, characterized by degeneration of the articular cartilage, hypertrophy of bone at the margins and changes in the synovial membrane. "Here the authors show that the RNA-binding protein ZFP36L1 is upregulated in chondrocytes of humans and mice with osteoarthritis, and that its knockdown in mouse joints protects chondrocytes against apoptosis by modulating the function of heat shock proteins." (PMID 30622281, 2019).
osteosarcoma (2 papers, 2024 to 2025). A usually aggressive malignant bone-forming mesenchymal neoplasm, predominantly affecting adolescents and young adults. "By overexpressing ZFP36L1 in osteosarcoma cell lines, we observed an increase in sensitivity to MTX." (PMID 41285712, 2025). "This study elucidates an intrinsic DNA damage repair mechanism in osteosarcoma cells treated with methotrexate (MTX) that can be effectively disrupted through the overexpression of ZFP36L1." (PMID 41285712, 2025). "In summary, decreased ZFP36L1 expression serves as an inherent mechanism enabling osteosarcoma to develop resistance to MTX therapy." (PMID 41285712, 2025). "Here, by using data analyses and in vivo experiments, we found that ZFP36L1 inhibited the lung metastasis of osteosarcoma (OS)." (PMID 37935976, 2024). "Our findings indicate that ZFP36L1 expression is downregulated in MTX-resistant osteosarcoma cells." (PMID 41285712, 2025).
T-cell leukemia (2 papers, 2014 to 2018). A malignant disease of the T-lymphocytes in the bone marrow, thymus, and/or blood. "Furthermore, it was also reported that deletion of murine Zfp36l1 and Zfp36l2 leads to perturbed thymic development and T-cell leukemia." (PMID 29449217, 2018).
Arthritis (1 paper, 2024). Inflammation of a joint. "We found that simultaneous deficiency of Zfp36, Zfp36l1, and Zfp36l2 in myeloid cells led to the spontaneous development of an early lethal phenotype, with severe arthritis, myeloid hyperplasia, bone resorption, and increased levels of cytokines and chemokines." (PMID 37903626, 2024).
bacterial pneumonia (1 paper, 2014). Acute infection of the lung parenchyma caused by bacteria (e.g., Streptococcus pneumoniae, Haemophilus influenzae, Chlamydia pneumoniae, Mycoplasma pneumoniae, and Legionella pneumophila). "In conclusion, these results imply that myeloid ZFP36 may fully compensate for loss of ZFP36L1 or that Zfp36l1-dependent mRNA expression does not play an integral role in the host defense against bacterial pneumonia." (PMID 25299049, 2014).
bladder tumor (1 paper, 2022). "Our previous study indicated that the coding gene of zinc finger protein 36 like 1 (ZFP36L1) mutated frequently in bladder tumor tissues and may be a potential suppressor for BC." (PMID 35359594, 2022).
cardiomyopathy (1 paper, 2022). A disease of the heart muscle or myocardium proper. "Previous studies have demonstrated that 2 members of the ZFP36 family play a role in cardiac function; deletion of Zfp36l1 and Zfp36 (also known as Ttp) causes embryonic heart defects and cardiomyopathy in iron deficiency, respectively." (PMID 35316214, 2022).
chronic asthma (1 paper, 2023). An asthma that is characterized by the development of persistent airway inflammation and recurrent attacks of breathlessness and wheezing, which vary in severity and frequency. "Mechanistically, it possible that expression levels of ZFP36L1 and ZFP36L2 are driven by different mechanisms in, particularly, severe/chronic asthma." (PMID 37928904, 2023).
chronic lymphocytic leukaemia (1 paper, 2014). "We originally reported on the pro-apoptotic function of ZFP36L1 in Ramos Burkitt B lymphoma cells and more recently in Rituximab-induced apoptosis of B-chronic lymphocytic leukaemia cells (BCLL) from which the human ZFP36L1 gene was originally isolated as an early response gene cDNA." (PMID 25014217, 2014).
chronic myeloid leukemia (1 paper, 2024). "In chronic myeloid leukemia (CML) cells, depletion of ZFP36L1 leads to decreased proliferation of CML cells upon treatment with tyrosine kinase inhibitor, while ZFP36L1 directly inhibits CDKN1A expression via post-transcriptional regulation." (PMID 38317146, 2024).
E. coli (1 paper, 2014). "To determine what other cell types express ZFP36L1 in the lung, we performed immunohistochemical staining of fixed lungs uninfected or infected with E. coli pneumonia." (PMID 25299049, 2014).
endometriosis (1 paper, 2017). The growth of functional endometrial tissue in anatomic sites outside the uterine body. "Transcripts for ZFP36L1 were significantly lower in women with endometriosis in both eutopic endometrium and ectopic endometriotic tissues compared to control fertile women." (PMID 28724967, 2017). "In order to examine if HuR/TTP axis contributes to the pathophysiology of endometriosis, we evaluated expression of Zfp36, Zfp36l1, Zfp36l2 and Elavl1 in eutopic and ectopic lesions obtained from syngeneic BALB/cByJ mouse model of endometriosis." (PMID 28724967, 2017).
Flavivirus Infections (1 paper, 2025). Infections with viruses of the genus FLAVIVIRUS, family FLAVIVIRIDAE. "ZFP36L1 combats flavivirus infections through the 5′-3′ XRN1 and 3′-5′ RNA exosome decay pathways." (PMID 39972499, 2025). "ZFP36L2 inhibited flavivirus infection solely through the 5′-3′ XRN1 RNA decay pathway, whereas ZFP36L1 inhibited JEV infection via the 5′-3′ XRN1 and 3′-5′ RNA exosome RNA decay pathways." (PMID 39972499, 2025). "In contrast with the antiviral mechanism of ZFP36L1 against flaviviruses in which ZFP36L1 recruits both the 5′-3′ XRN1 and 3′-5′ RNA exosome pathways to degrade flavivirus RNA, ZFP36L2 impedes flavivirus infection through a 5′-3′ XRN1-mediated RNA decay pathway." (PMID 39972499, 2025). "Therefore, the ZFP36L1 and ZFP36L2 proteins may serve a dual purpose during flavivirus infection by defending against the virus and downregulating the host’s inflammatory response, to maintain a balance between the control of viral replication and the prevention of excessive inflammation." (PMID 39972499, 2025).
hepatic disorders (1 paper, 2025). "Finally, several miRNAs are involved in ZFP36L1 and ZFP36L2 regulations and are deregulated in hepatic disorders (e.g., mir-96 or miR-124-3p for ZFP36L1; miR-409-3p, miR-375 or miR-429 for ZFP36L2)." (PMID 39941720, 2025).
lung adenocarcinoma (1 paper, 2022). A carcinoma that arises from the lung and is characterized by the presence of malignant glandular epithelial cells. "Consistent with the SCLC cell line data, RNA-sequencing from human SCLC tumors shows that ZFP36L1 mRNA expression is markedly reduced in SCLC compared to lung adenocarcinoma." (PMID 36008402, 2022). "This was confirmed at the protein level by immunohistochemistry (IHC) for ZFP36L1 using human lung tumor tissue microarrays (TMAs) where ZFP36L1 protein levels were significantly lower in SCLC TMAs compared to lung adenocarcinoma TMAs." (PMID 36008402, 2022).
metastasis (1 paper, 2021). The spread or migration of cancer cells from one part of the body (where they first appeared) to another. "ZFP36L1 down-regulation was closely associated with advanced tumor invasion (p = 0.013), advanced lymph node metastasis (p = 0.018), advanced clinical stage (p = 0.001)." (PMID 34465330, 2021).
multiple sclerosis (1 paper, 2023). A progressive autoimmune disorder affecting the central nervous system resulting in demyelination. "Characterisation of ZFP36L1 in the context of multiple sclerosis and functional immunological effects connected to the susceptibility to the disease, according to a study." (PMID 36982508, 2023).
myocarditis (1 paper, 2025). Myocarditis is a condition that is characterized by inflammation of the heart muscle (myocardium). "Our findings demonstrate that miR-93-3p directly targets 3′UTR of EIF4EBP1, consistent with prior studies showing that miR-93-3p alleviates renal injury by targeting NFAT5, promotes cellular proliferation and migration via targeting ZFP36L1, and modulates myocarditis by regulating TLR4 expression." (PMID 40900833, 2025).
neuroblastoma (1 paper, 2022). Neuroblastoma (NB) is the most common solid, extracranial childhood tumor. "ZFP36L1 is likewise expressed at low levels in other ASCL1-positive neuroendocrine tumors including neuroblastoma, that like SCLC, are dependent on ASCL130, suggesting that low ZFP36L1 expression is a common feature across high-grade neuroendocrine tumors." (PMID 36008402, 2022).